CCL2 (C-C motif chemokine ligand 2)
Diseases named in the same sentence as CCL2 in open-access papers (continued):
Sharing a sentence is not in itself a finding about the gene and the disease.
COVID-19 (continued). "Similarly, proinflammatory M1-like macrophages that express high levels of the chemokines CCL2, CCL3 and CXCL10 are abundant in BAL fluid from patients with severe COVID-19, suggesting a pathologic role for inflammatory lung macrophages in COVID-19 as well." (PMID 35271686, 2022). "Transcriptome analysis of BALF samples indicated that the levels of pro-inflammatory chemokines such as CXCL1, CXCL2, CXCL6, CXCL8 (IL-8), CXCL10 (IP-10), CCL2 (MCP-1), CCL3 (MIP-1A), and CCL4 (MIP-1B) are elevated in patients with COVID-19, which correlated with disease severity." (PMID 36111104, 2022). "Moreover, the levels of IL-8, CCL2, CCL3, CCL4, CCL7, CCL12, and CX3CL1 were higher in both the serum and CSF samples of COVID-19 cases with neurological syndrome (NS)." (PMID 35464491, 2022). "Furthermore, TUG1 had a positive correlation with CCL2 and TNF-α, implying that TUG1 is involved in CCL2 and TNF-α production, which explains its role in COVID-19." (PMID 35982898, 2022). "Specifically, patients with severe COVID-19 and high body mass indices tend to have increased IL-6 levels, endothelial injury, IFN activation, and cytokine profiles (e.g., IFN-γ, IL15, IL17, MCP1/CCL2, MIP1-beta/CCL4) that suggest macrophage recruitment." (PMID 36289507, 2022). "Changes in chemokine levels in peripheral blood of COVID-19 and influenza patients have been addressed by multiple studies, in particular CXCL9, CXCL10, CXCL11, CXCL16, CCL2, and CCL5 were altered in patients as compared to controls, and levels correlated to disease severity." (PMID 35371005, 2022). "Among COVID-19 patients, the most common disorders of cytokines and chemokines are increased levels of IL-1β, IL-2, IL-6, interleukin-7 (IL-7), IL-10, TNF-α, CRP, chemokine ligand 2 (CCL2), as well as an increase or decrease in the concentration of IFN-γ." (PMID 36294388, 2022). "COVID-19 triggers signaling cascades in response to viral contact, leading to the release of type I interferons, cytokines, and chemokines (IL-1β, IL-2, IL-6, IL-17, TNF-α, G-CSF, IFN-γ, CXCL10, CCL2 and CCL3, i.e., the cytokine storm)." (PMID 35982898, 2022). "As a result, early monitoring of CCL2 and CCL11 levels and responding on any elevations could be a potential method for preventing COVID-19 from advancing from mild to severe." (PMID 35958594, 2022). "Patients with severe COVID-19 typically have increased serum levels of IL-6, IL-8/CXCL8, CXCL9, CXCL10, TNF-α, MCP1/CCL2, RANTES/CCL5, IL-18, and MIP-1α/CCL3, which promote a sustained pro-inflammatory state that may persist for up to 60 days." (PMID 36289507, 2022). "Higher concentrations of CXCL8 and CCL2 in the plasma, with reduced mRNA expression presumably through negative feedback mechanisms, as well as CMV-positive status, correlated with more severe courses of COVID-19." (PMID 36232655, 2022). "Together, excessive M-CSF-driven monocyte/macrophage proliferation and CCL2/CCL7 activation and chemotaxis could be the mechanism of severe and fatal COVID-19 pathogenesis." (PMID 35386707, 2022). "Between COVID-19 patients and healthy controls, median chemokine concentrations (CCL2 and CCL4) were not statistically significant (P > 0.05)." (PMID 35958594, 2022). "In this study, IL-1 β, IL-2, LTB-4, CCL-2, and IL-8 levels were higher in all COVID-19 patients (survivors and non-survivors) compared with the levels in the healthy control group." (PMID 36294868, 2022). "We found significant direct correlations between galectin-3, CCL2, PON1, IL-6, IL-10, CRP, ACE2, and angiotensin II concentrations in COVID-19 positive patients as well as with aminotransferase activities and triglycerides, and inverse correlations with HDL-cholesterol." (PMID 34205807, 2021). "In this study, 44 potential targets were obtained through the intersection of the disease targets of COVID-19 and the action targets of AE, which are mainly related to inflammatory or immune factors, such as IL-6, MAPK1, MAPK8, IL1B, RELA, CXCL-8, CCL2, and PTGS2." (PMID 33658066, 2021).
COVID-19 (continued). "HuR may also be involved in the pathogenesis of COVID-19 by its ability to increase inflammation, as SARS-CoV-2 infection induces TNF-α, IL-6, and CC-chemokine ligand 2 (CCL2)." (PMID 35011584, 2021). "Besides the cytokines, several other small chemical molecules or chemokines such as CCL2 (MCP1), CCL3 (MIP1α), CXCL10 (IP-10) have been reported to be higher in the serum of severely ill patients with COVID-19." (PMID 34066983, 2021). "PON1 activity was the parameter with the greatest power to discriminate between patients who were either positive or negative for COVID-19, while their levels of CCL2 and galectin-3 were similar." (PMID 34205807, 2021). "Our data demonstrated strong enrichment of CCL2/19/20, CXCL10, GM-CSF, IL-6/8/15, S100A9, SCGF, TNF and TREM-1 in COVID-19, which could potentially play a critical role on the pathogenesis of the disease." (PMID 34238349, 2021). "Moreover, a significant correlation between COVID-19 severity and the serum concentrations of IL-1, IL-2, IL-6, IL-7, IL-10, TNF-α, G-CSF, CCL2, CCL3, CXCL8, and CXCL10 has been observed." (PMID 34209845, 2021). "Indeed, elevated levels of CCL2, CXCL10, IL-6 and TNFα have been identified in severe COVID-19 patients compared to patients with a mild form of the disease." (PMID 34452468, 2021). "PIMS-TS children had significantly elevated levels of cytokines, IFNγ, IL-2, TNFα, IL-1α, IFNα, IFNβ, IL-6, IL-15, IL-17A, GM-CSF, IL-10, IL-33 and IL-Ra; elevated chemokines, CCL2, CCL19, CCL20 and CXCL10 and elevated VEGF, Granzyme B and PDL-1 in comparison to COVID-19, seropositive and controls." (PMID 33813138, 2021). "Analysis of plasma from patients with COVID-19 has revealed increases in cytokines, including IL-1β, IL-2, IL-6, IL-7, IL-10, TNFα, monocyte chemoattractant protein (MCP1/CCL2), granulocyte colony stimulating factor (G-CSF), and macrophage inflammatory protein 1α (MIP1α/CCL3)." (PMID 34251989, 2021). "While CXCL9, CXCL10 and CXCL11 expression levels were increased both in moderate and severe disease compared to healthy levels, IL1β, IL6, TNF as well as CCL2, CCL3, CCL4 and CCL7 were expressed at higher levels in lung macrophages from patients with severe COVID-19." (PMID 34367190, 2021). "Finally, IL-6, MAPK3, MAPK1, MAPK14, MAPK8, IL-1β, CCL2, EGFR, PPARG, and NOS2 were declared key targets of XFBD for COVID-19." (PMID 35185537, 2021). "In addition to the chemokines MCP-1/CCL2 and MIP-1α/CCL3, which were increased in COVID-19 patients, IL-6 and TNF-α production also depends on NF-κB activation." (PMID 33232303, 2021). "In this study, we built a single-cell immune reference from multiple inflamed disease tissues and identified two inflammatory macrophage states, CXCL10+ CCL2+ and FCN1+ inflammatory macrophages, that were shared between COVID-19 and inflammatory diseases such as RA, CD, and UC." (PMID 33879239, 2021). "In accordance with this, COVID-19 tissue studies show increased expression of CCL2 and CCL7, known to be chemotactic for macrophages, thus stressing the central role of the cytokine storm in COVID-19 pathogenesis and highlighting a potential therapeutic intervention in severe disease." (PMID 33950285, 2021). "In addition, CCL2 and CCL8 were found elevated in postmortem lung specimens from COVID-19 patients compared to lung biopsies from healthy controls, thus corroborating the role of the cytokine storm in COVID-19 severity." (PMID 34209845, 2021). "IL-6, CXCL10, CXCL9, CCL2, IL1-Ra, IL-10, G-CSF and TNF-α were the cytokines with the highest contribution to dimension 2 in the PCA and were significantly increased in acute COVID-19 patients in comparison to HC." (PMID 34572439, 2021). "The analysis of the plasmatic levels of inflammatory chemokines and cytokines in patients with COVID-19 and MIS-C showed higher levels of IL-6, CXCL8, CCL2/MCP-1, CXCL9/MIG, and CXCL10/IP-10 in MIS-C, whereas CCL5 levels were significantly higher in the COVID-19 group." (PMID 33841438, 2021).
COVID-19 (continued). "One presents a moderate increase, similar to that of negative COVID-19 hospitalized patients, and another presents very high CCL2 levels—more than 20 times higher than those of healthy individuals." (PMID 34205807, 2021). "Furthermore, the involvement of C5a in the inflammatory process of COVID-19 is supported by identifing in patients with COVID-19, increased monocyte production of inflammatory cytokines, such as IL-6, TNF-α, and CCL2." (PMID 33669011, 2021). "Interestingly, in lung tissues, CCL2 and other chemokine expression are decreased by ACE2, but up-regulated during a COVID-19-induced cytokine storm." (PMID 34085037, 2021). "Clinical studies have shown elevated inflammatory cytokines, including tumor necrosis factor-alpha (TNF- α), interleukins (IL; IL2, IL6, IL7, IL8, IL9, and IL10), chemokines (CXCL10, CCL2, IP10, MCP1), and colony-stimulating factors (G-CSF, GM-CSF) in COVID-19 patients compared to a healthy person." (PMID 34513735, 2021). "Indeed inflammatory chemokines CCL2, CCL3 and CCL4 have been found at higher concentrations in the airways compared to the plasma in patients with severe COVID-19." (PMID 34614036, 2021). "Most patients with severe COVID-19 exhibited large amounts of pro-inflammatory cytokines and chemokines, such as IL-2, IL-6, IL-7, TNF-α, granulocyte colony stimulating factor (GCSF), CXC-chemokine ligand 10 (CXCL10), CC-chemokine ligand 2 (CCL2), and CCL3." (PMID 33987176, 2021). "Another study showed that Shufeng Jiedu prescription may prevent COVID-19 through its active ingredients likely quercetin, luteolin, wogonin, and kaempferol by targeting TNF, IL-10, IL-2, IL-6, STAT1, and CCL-2." (PMID 34861881, 2021). "Subsequently, to further determine whether SARS-CoV-2 infection in AAV/hACE2 mice model could also induce proinflammatory mediators as shown in severe COVID-19 patients, RNA levels of TNF-α, IL-1β, IL-6, CCL2, and CXCL10 in mice lung homogenates were measured." (PMID 34379705, 2021). "Recent clinical investigation reveals that COVID-19 mild patients had high level of IL1B, IFNγ, CXCL10/IP-10 and CCL2/MCP-1, while patients requiring ICU admission had higher level of GCSF, CXCL10/IP-10, CCL2/MCP-1 and CCL3/MIP-1A." (PMID 32228226, 2020). "Consistently, in this study we found the expression of a large number of cytokines are significantly elevated in COVID-19 patients BALF samples compared to control, including pro-inflammatory cytokines CXCL1, CXCL2, CXCL6, CXCL8, CXCL10/IP-10, CCL2/MCP-1, CCL3/MIP-1A and CCL4/MIP1B." (PMID 32228226, 2020). "The cytokine storm landscape of COVID-19 patients was further demonstrated in a retrospective study showing higher concentrations of IL-2, IL-7, IL-10, G-CSF, C-X-C motif chemokine ligand (CXCL)-10, C-C motif chemokine ligand (CCL)-2, CCL-3, and TNF-α in the plasma of severe COVID-19 patients." (PMID 33584335, 2020). "In our study, we first showed that despite similar respiratory severity, plasma concentrations of numerous cytokines characterizing the “cytokine storm” (i.e. IL-1β, IL-6, IL-8, IL-15, TNF-α, CCL2, CCL4, CCL19, CCL20, TGF-α) were lower in COVID-19 compared to non-COVID-19 patients." (PMID 33272291, 2020). "Furthermore, in a kinetic study, the plasma CXCL8, CCL2 and CCL7 levels were higher in fatal cases compared to the mild and/or severe cases of COVID-19." (PMID 33613280, 2020). "The “cytokine storm” concept is derived from the observation that COVID-19 patients requiring intensive care unit admission presented elevated circulating concentrations of CXCL10, CCL2, and TNFα as compared to those in which the infection was mild or moderate." (PMID 32983172, 2020). "In summary, we speculate that DYY may play an anti-inflammatory and immunoregulatory role in COVID-19 by acting on multiple target proteins, such as IL6, ILIB, and CCL2." (PMID 32536965, 2020).
COVID-19 (continued). "Transcriptional analysis of BALF further revealed high levels of IFN‐Υ induced protein-10 (IP‐10) and various chemokines like MCP‐1, CCL2, and CCL7 in BALF of severe COVID-19 patients, which correlated with increased infiltration of monocyte/Macrophages in their lungs." (PMID 33178021, 2020). "Compared to lung biopsies from uninfected individuals, post-mortem lung samples from COVID-19 male patients older than 60 years demonstrated robust expression of CCL2, CCL8 and CCL11, with no IFN-I and IFN-III detection." (PMID 33613280, 2020). "Thus, the aim of this study was to investigate the potential association between genic variants at rs1024611 (A>G), rs10774671 (A>G), and rs10406145 (G>C) of CCL2, OAS1, and DPP9 genes, respectively, and the severity of COVID-19 in a population from Quito, Ecuador." (PMID 38694517, 2024). "In addition, CCL2 expression exhibited higher levels in classical monocytes and dendritic cells, while an upregulation of IL10 mRNA was detected in monocytes and CD4+ T cells of COVID-19 patients." (PMID 39625479, 2024). "For instance, interventions designed to inhibit the signaling pathways of CCL2 and CXCL10 may help to reduce excessive immune cell recruitment and activation, thereby limiting inflammation and preventing the escalation of lung injury in COVID-19 patients." (PMID 39203987, 2024). "The systemic cytokine profiles observed in patients with severe COVID-19 show similarity to those observed in activated macrophages, with increased production of IL-6 and IL-7, tumor necrosis factor (TNF), and the inflammatory chemokine CC–chemokine ligands CCL2 and CCL3." (PMID 37892134, 2023). "The mediators CCL3, CCL4, CCL2, CCL5, IL-12, IL-15, IL-1Ra, and PDGF were higher in healthy volunteers, while the mediators CCL11, CXCL10, IL-1b, IL-6, TNF-a, IFN-g, IL-17, IL-9, IL-10, IL-13, FGF-basic, G-CSF, GM-CSF, IL-7, and IL-2 were increased in COVID-19 positive patients." (PMID 37903875, 2023). "Indicative cytokines in severely ill COVID-19 patients are characterized by boosted expression of IL-6, TNF-α, IL-17 macrophage inflammatory proteins 1-α (MIP-1α), MCP3, GM-CSF, IL-2, and IP-10, in addition to the elevated chemokines (IP-10, CCL2/MCP1, CXCL1, CXCL5)." (PMID 36081516, 2022). "Additionally, positive correlations between admission IL-8/CXCL8, MCP-1/CCL2, IL-10, and C-reactive protein plasma levels and Δoxygen supply during hospitalization could predict COVID-19 worsening, and some studies partly corroborate these findings." (PMID 36035415, 2022). "Significant levels of macrophage chemo-attractants such as CXCL10 and CCL2/MCP-1, as well as neutrophil chemo-attractants like CXCL2 and CXCL8, enhance immune cell migration to the site of infection, which is consistent with mononuclear cell infiltrates in COVID-19 patients’ lung tissues." (PMID 35958594, 2022). "CCL2/CCR2 are critical for monocyte and macrophage migration, a potential mechanism may be monocyte infiltration into the lungs via airway specific expression of CCL2/CCR2 in patients with severe COVID-19." (PMID 35749425, 2022). "A number of studies have shown that the sign of COVID-19 was the cytokine storm with elevated levels of interleukin-6 (IL-6), IL-1β, complement C1r (C1R), tumor necrosis factor-alpha (TNF-α), chemokine (C-C-motif) ligand 2 (CCL2), and granulocyte-macrophage colony-stimulating factor (GM-CSF)." (PMID 35726234, 2022). "In sensitivity analysis using genetic associations leaving out the UK Biobank rather than 23andMe, monocyte chemotactic protein-1 (MCP1; CCL2) was nominally positively associated with any COVID-19 and MIP1b was also nominally inversely associated with hospitalized COVID-19." (PMID 34163532, 2021). "Another characteristic of severe COVID-19 patients is the cytokine storm: over-production of numerous cytokines and chemokines such as interleukin-6 (IL-6), tumor necrosis factor-α (TNF-α), monocyte chemotactic protein-1 (CCL2), and chemokine (C-X-C motif) ligand 10 (CXCL10)." (PMID 34764867, 2021).
COVID-19 (continued). "Moreover the role of microbiota in modulating host immune response, and potentially influencing disease severity also in COVID-19, is confirmed by the inverse correlation of bacterial species depleted in COVID-19 patients, with plasma concentration of several cytokines (IL10, TNF-α, CXCL10, CCL2)." (PMID 34070662, 2021). "Consistently, the metatranscriptomic sequencing of the BALF discovered that COVID-19 patients showed marked hypercytokinemia and up-regulated IFN-stimulated genes, especially significantly elevated expression of chemokines, such as CXCL17, CXCL8, CCL2, and CCL7." (PMID 33987176, 2021). "To investigate the role of cytokines and chemokines in the inflammatory status of COVID-19 and MIS-C, we measured plasma levels of IL-1ß, IL-2, IL-4, IL-5, IL-6, IL-10, TNF-α, IL-17A, IFN-α, IFN-γ, CXCL10/IP-10, CXCL8/IL-8, CXCL9/MIG, CCL5/RANTES, and CCL2/MCP1." (PMID 33841438, 2021). "Transcriptomic studies revealed remarkably enhanced expressions of CCL2, CXCL8, CSF3, CSF2, and CXCL10 in Calu-3 cells infected with SARS-CoV-2, inflammatory factors that were shown to be strongly elevated in the serum of patients with severe clinical symptoms of COVID-19." (PMID 34578229, 2021). "We found that severe COVID-19 patients displayed, as extensively already reported, high level of circulating inflammatory cytokines, including IL-6, TNF-α, IL-1β and chemokines such as CXCL-10, CCL-2 and CXCL-8 contributing to the diffuse inflammatory status and the so-called cytokine storm." (PMID 34473805, 2021). "CCL2 and CXCL10 are chemokines, CCL2 facilitates the migration and infiltration of monocytes/macrophages to sites of inflammation produced by either tissue injury or infection, CXCL10 could drive longer duration of mechanical ventilation during COVID-19 ARDS." (PMID 34489974, 2021). "Another popular candidate, Lianhuaqingwen (LH), was shown to significantly inhibit SARS-CoV-2 replication in Vero E6 cells and markedly reduce production of pro-inflammatory cytokines (TNF-α, IL-6, CCL-2/MCP-1 and CXCL-10/IP-10), suggesting that it might be a potential option for COVID-19 treatment." (PMID 33643033, 2020). "Concordantly, for downstream genes of AP-1, the expression levels of some chemokine genes (e.g., CCL2, CXCL1, CXCL2, and CXCL10) were downregulated, while the expression levels of immune negative regulation genes (e.g. BCL3, NFKBIA, SOCS3, and TNFAIP3) were upregulated during the COVID-19 recovery." (PMID 33361761, 2020). "In addition, this study analyzed the transcriptome of bronchial epithelial cells and the serum cytokine and chemokine profiles of deceased COVID-19 patients, and confirmed an increase in inflammatory chemokines like IL-6, IL1RA, CCL2 and CCL8, suggesting immunologic misfiring in COVID-19." (PMID 32887790, 2020). "Finally, since MAFB-dependent factors like IL-10, SPP1, CCL2, and CXCL13 are biomarkers for COVID-19 severity, we next assessed whether additional MAFB-dependent soluble factors might also predict COVID-19 severity or outcome." (PMID 37917179, 2023). "We found that the high expression of C1R, CCL2, and TNFRSF1A genes was particularly associated with the low survival in GBM patients, while other 41 DEGs enriched in the pathway of coronavirus disease-COVID-19 were not significantly connected with the overall survival of GBM patients." (PMID 35726234, 2022). "Moreover, there were 16 kinds of CCGFs, including HGF, CXCL8/IL-8, CCL7/cP-3, CCL2/McP-1, CXCL9/MIG, CXCL10/IP-10, IL-6, IL-18, IL-2, M-CSF, IL-1Rα, IL-2Rα/CD25, IFN-γ, CC L3/MIP-1α, FGF, and SCF which were abnormally elevated in patients who died from COVID-19." (PMID 35528178, 2022). "Elevated concentrations of CCL2 and CCL8 were also observed in BAL samples from patients with COVID-19, relative to patients with pneumonia secondary to nonviral pathogens (q < 0.05, Mann-Whitney)." (PMID 38502186, 2024).